TLR2 (toll like receptor 2)
Diseases named in the same sentence as TLR2 in open-access papers (continued):
Sharing a sentence is not in itself a finding about the gene and the disease.
acne (continued). "The authors pointed out that acne prevention could be performed with the modulation of TLR2, the support for commensal growth of S. epidermidis and the inhibition of pathogenic C. acnes growth, biofilm and virulence factors." (PMID 33171837, 2020). "We monitored the most common inflammation markers expressed in macrophages because tissue macrophages surrounding the pilosebaceous unit in acne lesions expressed high levels of TLR2 and correlated with the degree of inflammatory nature of the clinical lesions." (PMID 31319552, 2019). "Moreover, there is a positive correlation between the severity of acne inflammation and TLR2 expression levels." (PMID 30120655, 2019). "Therefore, the P. acnes-induced inflammatory response participates in acne pathogenesis, at least in part due to the activation of TLR2 and its downstream signaling pathways, namely, the MAPK and NF-κB pathways." (PMID 30120655, 2019). "TLR-2 expression is found to be up-regulated in clinical acne lesions." (PMID 29507345, 2018). "Moreover, nuclear factor (NF)-κB, activator protein (AP)-1, pro-inflammatory cytokines (TNF-α, IL-1β, IL-6, and IL-8), and metalloproteinases (MMP) are activated via upregulation of TLR-2 in facial acne lesions of patients." (PMID 29507345, 2018). "TLR2 expression is increased in the epidermis and monocytes isolated from acne patients compared to healthy controls, and this increase might be a result of C. acnes-induced inflammatory events." (PMID 30319618, 2018). "A role for S. aureus in acne and rosacea can be hypothesized based on S. aureus’ ability to stimulate TLR2, for example via alpha toxin." (PMID 27151386, 2016). "In acne, Propionibacterium acnes probably contributes to inflammation via stimulation of TLR2." (PMID 27151386, 2016). "P. acnes is considered to be a trigger of exaggerated TLR2 mediated immune responses in acne." (PMID 25153527, 2014). "Inhibition of TLR2 surface expression by keratinocytes could be one of the anti-inflammatory mechanisms of zinc salts in acne." (PMID 25157359, 2014). "It has been reported that TLR2 was sufficient for NF-kappaB activation in response to P. acnes and activation of TLR2 resulted in an inflammatory cytokine response, which is thought to be of crucial importance in acne vulgaris." (PMID 24053623, 2013). "Interestingly, correlation between skin hydration levels and the percentage of classical monocytes TLR2-expressing could be useful in helping to select cosmetics and skincare products for patients with acne in clinical settings." (PMID 41010653, 2025). "Thus, Zn-containing samples may attenuate the inflammatory response in acne-like mice by inhibiting the TLR2/NF-κB pathway." (PMID 40507073, 2025). "Furthermore, Zn supplementation downregulated the expression of TLR2, IκBα, and IKKβ, which may exert its anti-acne effect by regulating related pathways." (PMID 40507073, 2025). "Therefore, modulation of TLR2 expression has been proposed as a novel target for acne treatment." (PMID 39588538, 2024). "Therefore, it has been hypothesized that Cutibacterium acnes stimulates cells during inflammatory acne by interacting with TLR2 and TLR4." (PMID 37687224, 2023). "Therefore, we hypothesize that the elevated PC and LPC identified in our study may be involved in the pathogenesis of acne by triggering TLR2 and TLR4-mediated signaling pathways to induce the production of inflammatory factors." (PMID 36120319, 2022). "C. acnes is able to trigger inflammation reaction through the TLR-2 pathway and TLR-2 is highly expressed in acne lesions; therefore, this candidate peptide appears to be a new TLR-2 modulator that could be clinically tested on patients presenting inflammatory acne lesions." (PMID 35563458, 2022). "Moreover, we suggest that the different mechanisms that could regulate the levels of the TLR2 and 4 receptors, or interact with their signaling pathways should be included more into the concepts of acne pathogenesis and treatment options." (PMID 29927962, 2018).
acne (continued). "In our research, we wanted to assess the level of expression of TLR2 and TLR4 on monocyte subpopulations in acne patients in the context of assessing the state of skin hydration, oiliness, pH, and erythema intensity using specialized probes." (PMID 41010653, 2025). "Monocyte subpopulations expressing TLR2 and TLR4 circulating in the peripheral blood of patients with acne vulgaris appear to be indifferent to altered skin parameters: level of oiliness, hydration, and skin pigmentation (phototype, erythema)." (PMID 41010653, 2025). "This study aimed to evaluate the percentage of monocyte subpopulations expressing TLR2 and TLR4, in relation to clinical data and skin function parameters, in patients with untreated acne vulgaris." (PMID 41010653, 2025). "In keratinocytes during acne vulgaris, Christie–Atkins–Munch-Petersen 1 factor (CAMP1) binds TLR2, and di- and tri-acylated lipoproteins engage TLR1/2 and TLR2/6 heterodimers, respectively." (PMID 39272974, 2024). "To address the pathogenesis of acne vulgaris, we examined the expression of TNF-α, IL-1β in serum, and TLR2/NF-κB signaling pathway in tissues." (PMID 37159798, 2023). "The therapeutic effects of 1064 nm Nd:YAG laser depends on its effect on the vascular component of inflammatory acne in addition to the alteration of cytokine release, including the upregulation of TGF-β and the downregulation of IL-8 and TLR-2." (PMID 35084634, 2022). "The expression of TLR2 and TLR4 were significantly elevated in the acne lesions in the Finnish group." (PMID 25153527, 2014). "As P. acnes exposure leads to increases in TLR2 (as well as TLR4) expression in NHEK, and TLR2 expression was reported within acne lesions in situ, we choose to further investigate the role of this receptor in keratinocyte and sebaceous gland function." (PMID 24011352, 2013). "The results obtained showed a weak negative correlation between the level of TLR2 expression on intermediate monocytes and the results of the corneometer measurement on the forehead (rho = −0.33, p = 0.042) in patients with acne vulgaris." (PMID 41010653, 2025). "C. acnes triggers the activation of the Toll-like receptors TLR-2 and TLR-4 on sebocytes and keratinocytes, initiating the release of pro-inflammatory cytokines such as IL-6, IL-8, and IL-12 from monocytes, markers that are notably elevated in acne lesions." (PMID 38791344, 2024). "Additionally, the AhR is able to modulate TLR2-mediated expression of TNF-α and IL-8 in human sebocytes, thereby highlighting its role in acne inflammation." (PMID 37344849, 2023). "Furthermore, C. acnes can be recognized by pattern recognition receptors such as TLR2 and TLR4, which mount immune responses against the bacteria, thus influencing acne development." (PMID 33849530, 2021). "Of note, TLR2 recognition of Candida albicans suppresses inflammatory responses via production of IL-10 and enhanced Treg survival but it is not known if TLR2 recognition in acne has the same consequences." (PMID 25153527, 2014). "Similarly, TLR2 and TLR4 as well as IL-8, IL-6, and TNF-α, were induced in acne lesions in the German group." (PMID 25153527, 2014). "APS may improve acne inflammation by inhibiting TLR2/NF-κB signaling pathway, while ABT does not inhibit NF-κB phosphorylation." (PMID 37159798, 2023). "So far, research on determining whether micro-current stimulation can inhibit the TLR2-mediated inflammatory response related to the main mechanism of acne has not yet been conducted." (PMID 35269651, 2022). "It has been shown that TLR-2 modulators can be used to treat acne without adverse events." (PMID 35563458, 2022). "Therefore, Cath-MH may have anti-inflammatory effects by binding LPS/LTA and blocking TLR2/4-mediated MAPK/NF-κB signaling pathways in macrophage cells and acne mouse models." (PMID 34955858, 2021).
acne (continued). "Moreover, SAA1 has been found to increase also in keratinocytes in response to TLR2 activation, which was further augmented when glucocorticoids were used in combination, suggesting a possible contribution of SAA to (steroid-induced) acne." (PMID 29927962, 2018). "Interestingly, the group with no sequence polymorphism (B3) corresponded to strains inducing low or moderate levels of CXCL8 production, producing a CAMP factor 1 not recognized by TLR2; all these strains were isolated from patients with moderate acne." (PMID 27902761, 2016). "Therefore, it is more likely that P. acnes has its specific role in acne pathogenesis not (only) via the TLR2 pathway but with its various products that could interact with the inflammatory pathways, which is definitely a challenging field for future studies." (PMID 29927962, 2018). "Clinically, acne lesions exhibit higher levels of CAMP factor and TLR2 than nonlesional skins, further substantiating that the CAMP factor of C. acnes is a key contributor to TLR2-related inflammation in acne." (PMID 37344849, 2023). "Although strains different from IA1 are not typically related to acne, CAMP factor belonging to IB and II phylotypes can induce intense production of CXCL8 (IL-8) in response to TLR-2 recognition of this virulence factor by keratinocytes." (PMID 35910763, 2022). "This study aimed to evaluate the expression of TLR2 and TLR4 receptors on classical, intermediate, and non-classical monocyte subpopulations in 38 women with acne vulgaris and to correlate the results with clinical features of the disease and selected skin parameters." (PMID 41010653, 2025). "However, we have demonstrated differences in the percentage of classical, intermediate, and non-classical monocyte subpopulations expressing TLR2 and TLR4 in patients with untreated acne vulgaris with selected skin parameters." (PMID 41010653, 2025). "Based on these findings, we propose that ATRA may exhibit dual effects in acne therapy by both affecting the expression of the negative regulator TNIP1 and attenuating TLR2-induced inflammation." (PMID 30319618, 2018).
pneumonia (61 papers, 2007 to 2026). An acute, acute and chronic, or chronic inflammation focally or diffusely affecting the lung parenchyma, caused by an infection in one or both of the lungs (by bacteria, viruses, fungi, or mycoplasma.). "Both reducted mortalities and K. pneumoniae-host disseminations were associated with TLR4 and TLR2 immune responses within the pneumonia mouse model." (PMID 36911530, 2023). "Another study also described an association between this SNP and the risk of both sepsis and pneumonia; the same associations were described for the Thr399Ile TLR4 polymorphism whereas the TLR2 polymorphism Arg753Gln was only associated with pneumonia." (PMID 35163998, 2022). "The TLR2 SNP rs5743708 (R753Q, GA/AA genotype, n = 12) is associated with a higher risk of pneumonia and invasive fungal infections in patients with acute myeloid leukemia undergoing chemotherapy." (PMID 35794908, 2022). "TLR2 SNP rs5743708 (R753Q, GA/AA genotype, n = 12) is associated with a higher risk of pneumonia and invasive fungal infections in patients with acute myeloid leukemia receiving chemotherapy." (PMID 35794908, 2022). "In particular, further research is required into the roles of TLR2 or TLR6 polymorphisms in pneumonia." (PMID 36428390, 2022). "As for pneumonia, carriage ofthe rs5743708 A allele (the TLR2 gene) predisposes to severeCAP; the heterozygous genotype of rs8177374 (the TIRAPgene) in combination with the GG genotype of rs5743708 (theTLR2 gene) has a protective effect against it." (PMID 35083399, 2021). "Subgroup analysis for TLR2 R753Q and Dectin-1 rs7309123 G/G genotype regarding susceptibility to pneumonia." (PMID 26963509, 2016). "Patients harboring either the TLR2 R753Q or the Dectin-1 rs7309123 G/G and G/G + C/G genotype were identified to have a significant higher risk for developing pneumonia in general, as well as atypical pneumonia and even pulmonary IFD." (PMID 26963509, 2016). "Here, we report the impact of Dectin-1 and TLR2 polymorphisms on susceptibility to different types of pneumonia including pulmonary IFD in patients receiving induction chemotherapy for acute myeloid leukemia." (PMID 26963509, 2016). "Patients carrying the TLR2 SNP rs5743708 (R753Q, GA/AA genotype, n = 12) also revealed a significantly higher susceptibility to pneumonia including IFD." (PMID 26963509, 2016). "TLR2 and TLR4 are crucial for recognition of Chlamydia pneumoniae in vivo, since infected TLR2/4 double-deficient mice are unable to control the infection as evidenced by severe loss of body weight and progressive lethal pneumonia." (PMID 22096480, 2011). "The results of our preliminary study of the relationship between TLR2 polymorphism and the onset of pneumonia imply that PRR polymorphisms also affect disease resistance in pigs." (PMID 21645307, 2011). "In contrast to wild type animals, mice double-deficient for TLR2 and 4 were unable to control the replication of the bacteria and succumbed to progressive pneumonia." (PMID 22096480, 2011). "Both control and TLR2-deficient mice developed a patchy pneumonia, with inflammatory exudates visible in the alveolar space." (PMID 21695078, 2011). "Failure of IFNγ to induce NO in TLR2/4 double-deficient cells represents one possible mechanism why TLR2/4 double-deficient mice are unable to control pneumonia caused by C. pneumoniae and succumb to the infection." (PMID 22096480, 2011). "Upon challenge with C. pneumoniae MyD88-deficient mice succumbed like TLR2/4-deficient mice to progressive pneumonia, although pulmonary IFNγ-levels were increased like in wild type mice six days post infection." (PMID 22096480, 2011). "Considering that the pneumolysin-deficient strain used here is a serotype 2 (derived from S. pneumoniae D39), we first investigated the impact of TLR2 deficiency on the course of pneumonia caused by WT S. pneumoniae D39." (PMID 17711480, 2008).
pneumonia (continued). "TLR2 KO mice displayed a strongly reduced early inflammatory response in their lungs during pneumonia caused by both pneumolysin-producing and pneumolysin-deficient pneumococci." (PMID 17711480, 2008). "Finally, carriers of either TLR2-rs5743708 or TLR4-rs4986791 polymorphism also displayed a significantly increased risk for developing pneumonia and more severe disease." (PMID 37766191, 2023). "TLR2 is associated with the incidence of pneumonia caused by Mycoplasma hyopneumoniae." (PMID 27036198, 2016). "Because of the functional relationship between TLR2 and Dectin-1 we next analyzed if a clustering of AML patients tested positive for the TLR2 R753Q polymorphism or carrying the Dectin-1 SNP rs7309123 G/G genotype might affect the frequency of pneumonia." (PMID 26963509, 2016). "Polymorphisms in the PRR genes may be related to disease susceptibility in pigs: pigs with a particular allele of TLR2 showed an increased tendency to contract pneumonia." (PMID 21645307, 2011). "rs5743708 may be the sole contributor to the association of the TLR2 gene with pneumonia." (PMID 36611413, 2022). "Besides, the reduction of TLR2 has been acknowledged as a prognostic factor in infections, such as pneumonia and its diminished expression may predispose SLE patients to infections in a similar way of genetic variants." (PMID 30692998, 2018). "Although TLR2 is considered the most important receptor for Gram-positive bacteria, our laboratory previously could not demonstrate a decisive role for TLR2 in host defence against pneumonia caused by a serotype 3 S." (PMID 17711480, 2008). "Gene expression analysis revealed significant upregulation of immune-related markers (TLR2, CLEC4E, PTX3, CXCL8, IL15RA) and notable SNP variations associated with pneumonia susceptibility." (PMID 40559821, 2025). "In an observational study, elderly patients with severe pneumonia exhibited lower levels of monocyte TLR2 and TLR4 expression, correlating with diminished serum concentrations of interleukin-1 (IL-1), interleukin-6 (IL-6), and TNF-α." (PMID 36829255, 2023). "TLR agonists are even being considered as treatments against pneumonia, as TLR2/6 and TLR9 agonists have been effective at reducing mortality when paired with oseltamivir during influenza A infection in mice." (PMID 36829255, 2023). "have shown reductions in TLR-2 & 4 and NF-κB P65 by miR-26a-5 mimic in the mouse alveolar macrophage severe pneumonia model, suggesting that miR-26a-5p regulates TLR/NF-κB signal pathway." (PMID 35491874, 2022). "A comparative analysis of the genotype/allele frequencies for the rs5743551 (TLR1), rs5743708 (TLR2), and rs4986790 (TLR4) polymorphisms was carried out depending on the outcome of pneumonia (recovery/death)." (PMID 34603755, 2021). "We also showed that the inflammatory cytokines such as IL-1α, IL-6, and IL-12 p40 in Mp-induced pneumonia are dependent on the TLR2 in mice." (PMID 34937175, 2021). "Most likely, the contribution of the alleles ofgenes TLR2 and TIRAP to CAP predisposition is determinedby pneumonia etiology." (PMID 35083399, 2021). "The TLR2 signaling activation during Gram-positive bacterial (S. pneumoniae) pneumonia increases the non-small cell lung cancer cell (NSCLC) metastasis." (PMID 32849610, 2020). "It is a highly inflammatory Toll-like receptor 2 (TLR2) ligand, and previous in vivo studies have demonstrated its ability to recapitulate pathological features of pneumonia and meningitis." (PMID 28049146, 2017). "Here, we evaluate the protective effect and the mechanism of MRSA murine pneumonia after pretreatment with Pam3CSK4, a TLR2 agonist." (PMID 26974438, 2016). "Our study is the first to summarize data from individual papers on the role of TLR2 SNPs in pneumonia/pneumococcal infection." (PMID 27725770, 2016).